TNF (tumor necrosis factor)
Diseases named in the same sentence as TNF in open-access papers (continued):
Sharing a sentence is not in itself a finding about the gene and the disease.
COVID-19 (continued). "Additionally, for serum TNFα levels, approximately 32 pg mL-1 was observed in patients hospitalized with COVID-19 as well as to CAR-T patients with cytokine release syndrome." (PMID 36911698, 2023). "IL-17, HIF-1 and TNF were involved in quercetin-mediated treatment in COAD/COVID-19 patients." (PMID 37704909, 2023). "The glycoprotein-S of the COVID-19 vaccine stimulates the release of TNF-α, IL-8, and IFN-γ." (PMID 38132239, 2023). "In particular, IBD patients under anti-TNF therapy appear to have no increased risk for critical COVID-19 courses, despite their slightly reduced humoral immunity." (PMID 37766088, 2023). "In addition, we also measured the expression levels of CD147 and TNF mRNA and miR-492 from whole blood of patients with COVID-19 through RT-q-PCR." (PMID 37630479, 2023). "A decreased TNFα production in Japanese COVID-19 patients may contribute to a less severe disease course." (PMID 38313435, 2023). "IL, IFN, TNF, and GM-CSF are the main cytokines involved in generating cytokine storms in COVID-19." (PMID 35883738, 2022). "A previous study suggested a reduction in T cell counts in COVID-19 patients and high levels of pro-inflammatory markers such as TNF-α, IL-6, IL-8, and IL-10 may be a potential reason for the killing of T cells." (PMID 35890093, 2022). "In severe COVID-19 cases, the production of pro-inflammatory cytokines, including IL-1β, IL-6 and TNF-α, is increased leading to the generation of cytokine storm, inducing futher unfovarable outcome and may eventually lead to lymphopenia." (PMID 35911748, 2022). "Moreover, elevated levels of TNF in the blood and tissues of patients with COVID-19 have been indicated in previous reports." (PMID 34983527, 2022). "The effect of anti-TNF in long COVID-19 patients could be a potential target for further research to establish the relationship between TNFα and COVID-19 recovery." (PMID 36405747, 2022). "Moreover, TNF-α expression was upregulated in both moderate and severe COVID-19 patients compared to controls, and this elevation was less than ten folds." (PMID 35982898, 2022). "In addition, it has been reported that patients on anti-TNFα who have completed their initial two-vaccine series rarely develop severe COVID-19, similar to the general population." (PMID 36298483, 2022). "It was already reported that monocytes/macrophages from patients with severe COVID-19 may be the main source of uncontrolled levels of the pro-inflammatory mediators TNF-α and IL-6 in the peripheral blood of the respiratory tract." (PMID 35891437, 2022). "The elevated cytokine levels of IFN-γ and TNF-α in NK cells of COVID-19 patients as we found by our ex vivo analysis, contradict with the reported decreased cytokine production when cells of COVID-19 patients are stimulated in vitro with either cytokines or tumour target cells." (PMID 36275702, 2022). "The IL-6, IL-1β, TNF-α, and IL-10 levels were consistently upregulated in patients with COVID-19." (PMID 36230930, 2022). "Increased serum alanine transaminase (ALT) and aspartate aminotransferase (AST) observed in patients with COVID-19 could also be due to the action of TNF and IFN-γ in hepatocytes." (PMID 36419185, 2022). "Therefore, further molecular and clinical studies are necessary to understand the real potential of anti-TNF inhibitors in COVID-19." (PMID 35631442, 2022). "Elevated serum IL-6 levels predict mortality in approximately 50% of HF patients, and high tumor necrosis factor (TNF)-α levels in patients with severe COVID-19 may exacerbate the development of HF." (PMID 36420258, 2022). "Anti-cytokine autoantibodies (e.g., antibodies against IFNα, IFNε, IL-6, IL-22, GM-CSF and TNFα) may also provide a potential target for COVID-19 treatment." (PMID 36341384, 2022). "Thus, active NRLP3 inflammasome has been observed in the myeloid cells of COVID-19 patients, and a combination of TNF-α and IFN-γ-mediated macrophage PANoptosis." (PMID 35066575, 2022).
COVID-19 (continued). "There are some common upper airway symptoms in allergic rhinitis and COVID-19 and hypersensitivity in the immune system, both of which involve phagocytic cells (e.g.: macrophages and monocytes) and release of cytokines (e.g.: IL-1 and TNF-α)." (PMID 35897044, 2022). "However, no previous studies postulated the effect of age on the levels of inflammatory mediators including IL-6 and TNF-α in COVID-19 patients." (PMID 36381078, 2022). "An early increase and high levels of TNF-alpha in COVID-19 predicts mortality." (PMID 36060521, 2022). "From these data, it can be postulated that in COVID-19 patients increased levels of aldosterone activate the NF-κB signaling pathway via the MR, which activates the expression of pro-inflammatory cytokines such as TNFα and IL-6." (PMID 35867189, 2022). "In addition, both TNF and IFN-γ are elevated in patients with COVID-19, and preclinical studies have suggested combined inhibition of TNF and IFN-γ signaling can decrease the effects of cytokine storm driven by PANoptosis." (PMID 36419185, 2022). "Indeed, the results of further clinical trials are necessary, to better elucidate the role and the timing of TNF inhibitors in COVID-19 treatment." (PMID 36289890, 2022). "The levels of IP-10, IL-15, IL-18, and TNF-α were exclusively increased in SOTRs with COVID-19." (PMID 35075453, 2022). "In two other studies of the Veterans Affairs Health Care System, neither thiopurines nor anti-TNF was associated with an increased risk of COVID-19 in IBD, and both vedolizumab and corticosteroids were independently associated with SARS-CoV-2 infection." (PMID 36556155, 2022). "Furthermore, sFas-Fc, which blocks FasL-mediated jurkat cell death, increased the levels of TNF-α transcripts of CD3-activated T cells from COVID-19 individuals." (PMID 35066575, 2022). "Moreover, since the inflammation in COVID-19 patients is partially driven by NF-κB and characterized by increased TNF-α and IL-6 production, we investigated the global effect of the HDAC6 inhibitor ITF3756 on purified human monocytes stimulated with TNF-α." (PMID 35592335, 2022). "Whether this decrease in adverse event rates might reflect a reduced serologic response to vaccination is yet to be defined, but recently observed data do indicate an impaired antibody production after vaccination against COVID-19 in anti-TNFα recipients." (PMID 35160092, 2022). "The functionality of T cells and NK cells, as well as the production of granzyme, perforin, CD107a, IFN-γ, and TNF in PBMCs from uninfected individuals and patients with severe/critical COVID-19, was evaluated by flow cytometry at baseline or after stimulation with PMA and Ionomycin." (PMID 36359755, 2022). "The pro-inflammatory state caused by the SARS-CoV-2 virus is the main pathophysiological process of the COVID-19, which is characterized by increased levels of serum interleukin-1,6 (IL-1,6) and tumor necrosis factor (TNF), resulting in “cytokine storm” and ARDS." (PMID 35355592, 2022). "High levels of IL-6, IL-8, and TNF-α were found in COVID-19 patients’ serum." (PMID 35805406, 2022). "Besides IL-1β, IL-6, and TNF, several cytokine storm-related factors are potential therapeutic targets for the treatment of severe COVID-19 patients." (PMID 34983527, 2022). "Monocyte-derived macrophages have also been linked as a possible source of pro-inflammatory cytokines, TNF, CXCL-8, IL-1, and IL-8 during severe COVID-19, therefore suggesting a strong association between monocyte-derived macrophages and COVID-19 disease severity." (PMID 36072602, 2022). "Spontaneous production of TNF-α also increased after COVID-19." (PMID 36579544, 2022). "TNF is an intensely studied proinflammatory cytokine, which can trigger either cell survival or cell death by regulating a complex inflammatory network, and its hyperproduction is related to the pathogenesis of COVID-19 as well." (PMID 35241045, 2022).
COVID-19 (continued). "Biological treatment targeted against TNF-α and IL-17 could play an important protective role against COVID-19 in psoriatic patients." (PMID 36016267, 2022). "We suggested that high production of TNF, TNFRSF13B, and IL32 might be associated with and can serve as markers for COVID-19 severity." (PMID 35983322, 2022). "Our data suggest that anti-TNF-α treatments may be beneficial to COVID-19 outcome through elicitation of protective immune response in RMD patients." (PMID 35757699, 2022). "In more severe cases, increased levels of IL-2, IL-7, IL-10, and TNF-α were observed, which may indicate an important role of specific cytokines and chemokines in driving COVID-19 progression." (PMID 35982454, 2022). "In this regard, recently, it was suggested that patients with any inflammatory disease using TNF inhibitors had a lower probability of hospitalization or the development of severe COVID-19 compared to patients diagnosed with an inflammatory disease but another treatment." (PMID 35631442, 2022). "Across CD4+, CD8+, and NK cells, we found cell cycle and redox state pathways were enriched for differentially expressed genes in more severe hospitalized COVID-19 cases; interferon pathways in less severe disease; and TNF signaling in community cases versus healthy volunteers." (PMID 35216673, 2022). "Patients with mild and moderate COVID-19 had similar levels of TNF-α than healthy subjects." (PMID 35508575, 2022). "Regarding TNF-α, patients from Lima had a mean level of 25.9 pg/ml (healthy) and 61.6 pg/ml (COVID-19), meanwhile, patients from Huaraz had levels of 89.0 pg/ml (healthy) and 120.6 pg/ml (COVID-19)." (PMID 35090394, 2022). "Severe COVID-19 is known to cause a cytokine storm, in which over-activated lymphocytes secrete many cytokines such as interleukins (ILs); (IL2, IL6, IL7, etc.), and tumor necrosis factor (TNF)." (PMID 35615724, 2022). "Furthermore, levels of IFN, IL, and TNF have been suggested as possible biomarkers of COVID-19 severity status." (PMID 35562935, 2022). "An example of how COVID-19 and endometriosis could contribute to each other’s pathogenesis is via tumor necrosis factor α (TNF-α)." (PMID 36361745, 2022). "NK cells from COVID-19 patients show reduced expression of IFNγ and TNFα." (PMID 38566903, 2022). "Here both M.tb and M.tb-EST12 significantly induced pro-inflammatory cytokines IL-6 and TNF-α expression, suggesting that M.tb-induced pro-inflammatory cytokines might possibly have implication on inflammation of severity COVID-19." (PMID 36003390, 2022). "However, patients with severe COVID-19 typically have high plasma levels of TNF-α, which is suggested to enhance inflammatory responses, thereby contributing to the severity of the disease." (PMID 36478862, 2022). "Recently, an investigation with a large cohort of patients proposed that serum IL-6 and TNF levels should be considered in the management and treatment of patients with COVID-19 to stratify prospective clinical trials, guide resource allocation and inform therapeutic opportunities." (PMID 35720401, 2022). "Interestingly, a significant correlation between the critical illness/intensive care unit (ICU) admission of COVID-19 patients and serum levels of IL-6 and TNF-α has been documented." (PMID 35456120, 2022). "Elevated levels of IL-6, IL-10, and TNF-α in COVID-19 patients promote the expression of PD-1 and T-cell immunoglobulin mucin 3 (Tim-3) on the surface of peripheral T cells that act as exhaustion signals, resulting in decreased T-cell function and memory T-cell activity." (PMID 35615369, 2022). "Thus, blocking TNF in individuals with COVID-19 is a potential immunomodulatory treatment by decreasing the production of other pathogenic cytokines." (PMID 35782361, 2022).
COVID-19 (continued). "COVID-19 is characterized by an overwhelming state of inflammation with an elevated level of circulating chemokines (e.g., MCP-1 and RANTES) and cytokines, such as IL-6, IL-8, and TNF-α eventually leading to a multi-organ dysfunction that has been called COVID-19 cytokine storm syndrome (CSS)." (PMID 35211011, 2022). "Drugs targeting TNF or its receptor in clinical studies in patients with COVID-19." (PMID 35223745, 2022). "TNF-α is one of the central cytokines involved in inflammation initiation and amplification in virus infections, and is reported to be elevated in critical COVID-19 cases, suggesting it as a proper indicator for in vitro drug screening." (PMID 35296098, 2022). "In our study, the cytokines IL-6, IL-10, and TNF-α were significantly upregulated in severe COVID-19 patients, especially in male patients, indicating that IL-6 antagonists and TNF-α inhibitors are more appropriate used in male patients to reduce both severity and mortality rate of COVID-19." (PMID 35237162, 2022). "Others have already shown that these therapies, particularly TNF inhibitors, reduce the ability of different COVID-19 vaccines (based on mRNA or adenoviral vector) to produce spike-specific antibodies, especially those that recognize SARS-CoV-2 variants, including B.1.617.2 (Delta)." (PMID 35536644, 2022). "Also, the effect of MAFLD on the progression of COVID-19 is determined by the rate of secretion of proinflammatory mediators such as TNF-α and IL-6." (PMID 36531832, 2022). "Indeed, severe COVID-19 cases have been reported to have high amounts of TNF in the germinal centers, thereby limiting appropriate immune responses." (PMID 36419185, 2022). "Recent data suggest that N-acetylcysteine may alleviate patient symptoms by reducing cytokine release, including TNF-α, during COVID-19." (PMID 36146616, 2022). "Similarly, high-level cytokines (e.g., IL-1β, IL-6, IL-8, IL-10, IFN-γ, and TNF-α, etc.)were registered in the blood of Coronavirus Disease 2019 (COVID-19) patients." (PMID 35350754, 2022). "Together with proinflammatory cytokines TGF-β, VEGF, IL-6 and TNF-α, this may lead to PF in COVID-19." (PMID 36268783, 2022). "Regarding the hyperinflammation, we observed BK1-8 was positively and significantly related to four out of five inflammation markers studied (CRP, ferritin, IL-1β, IL-6, and TNF-α), suggesting a potential role of this peptide in patients with COVID-19’ inflammation." (PMID 35812405, 2022). "The possibility of a predisposing role for COVID-19 in TNF inhibitors should be taken into account, as they represent the majority of the previous asymptomatic COVID-19 patients, despite the results did not achieve statistical significance." (PMID 35964130, 2022). "Due to certain similarities between COVID-19 and RA, some treatments used to treat COVID-19 patients have been borrowed from rheumatologists: hydroxychloroquine, glucocorticoids, IL-6, IL-1 inhibitors, and anti-TNF and Janus Kinase (JAK) inhibitors." (PMID 36226148, 2022). "Another reason for the high death rate of COVID-19 in patients with dementia is the cytokine storm, where it has been shown that dementia patients have elevated proinflammatory cytokines, such as tumor necrosis factor-alpha, interleukin-1, and interleukin-6, which increases the death rate." (PMID 35215217, 2022). "Elevated levels of cytokines such as IL1B, IL7, IL8, IL9, and IL10, monocyte chemoattractant protein and tumor necrosis factor (TNF), among others, in COVID-19 have been reported and elevated proinflammatory cytokine levels have been found to correlate with disease severity." (PMID 35172279, 2022). "Early observations from clinical data support the idea that anti-TNF Abs, such as infliximab or adalimumab may reduce the mortality rate in patients with COVID-19." (PMID 34983527, 2022).
COVID-19 (continued). "All the natural products evaluated in this work might reduce the severity of COVID-19 symptoms by significantly decreasing the production of the pro-inflammatory mediator TNF-α." (PMID 35891437, 2022). "The immunopathology of COVID-19 is characterised by an elevation of IL-6 and TNF-α." (PMID 35843719, 2022). "Besides IL-6, patients with severe cases of COVID-19 have higher plasma levels of other elements of cytokine storms, including IL-2, IL-7, IL-8, IL-10, and tumor necrosis factor-α (TNF-α)." (PMID 35295802, 2022). "In our cohort of hospitalized COVID-19 patients, the activation of Vδ2+ T lymphocytes is inhibited by atorvastatin in a dose-dependent manner, resulting in a significant reduction in the expression of the pro-inflammatory cytokines TNF-α, IFN-γ, and IL-17." (PMID 36359845, 2022). "Severe COVID-19 courses are characterized by hyperinflammation and cytokine storms, with significantly higher serum levels of interleukin (IL)-6, IL-8, IL-10, IL-2R and tumor necrosis factor (TNF)-alpha." (PMID 34608263, 2022). "Therefore, trials of anti-TNF-based therapy (e.g., using adalimumab, etanercept, or golimumab monoclonal antibody) have also been suggested for hospitalized COVID-19 patients." (PMID 35992513, 2022). "Additionally, Cluster 5 showed a synergistic inflammatory signature through cotreatment with TNF-α and IFN-γ, implying an association with COVID-19 severity." (PMID 36229591, 2022). "Though the specific cause of hyperferritinemia is unknown, higher proinflammatory cytokines such as TNF-alpha, IL-1, IL-6, etc., in COVID-19 patients are thought to enhance serum ferritin production." (PMID 35982484, 2022). "While several studies have shown that elevated concentrations of IL-8 and TNFα correlate with severity of COVID-19, IL-6 dysregulations appear to have the most profound effect in CS, with high concentrations associated with respiratory failure, poor prognosis and mortality." (PMID 35500008, 2022). "Some observations of individuals already taking anti-TNFα therapies that showed milder symptoms after getting positive for COVID-19 might dissipate this concern (Abdullah and others 2020)." (PMID 35674675, 2022). "The data obtained show that mothers affected by COVID-19 have an increase in pro-inflammatory factors (TNF-α, TGF-β, IL-2, IL-6, IL-8) compared to controls; this increase could generate a sort of “protection of the fetus” from virus attacks." (PMID 35408809, 2022). "Indeed, serum levels of inflammatory mediators and markers, including interleukin (IL)-6, C-reactive protein (CRP), IL-1β, IL-10, CXCL9, CXCL10, ferritin, and tumor necrosis factor-α (TNF-α) are elevated in cases of COVID-19." (PMID 35053424, 2022). "Furthermore, a decrease in serum levels of pro-inflammatory cytokine TNF-α and an increase in anti-inflammatory cytokine IL-10 in patients with COVID-19 following MSC transplantation suggests efficient regulation of cytokine storms." (PMID 36078094, 2022). "For instance, serum levels of pro-inflammatory cytokines, such as interleukin-6 (IL-6), tumor necrosis factor-alpha (TNFα), and IL-10, are elevated in patients with COVID-19, especially in those treated in the intensive care unit, correlating positively with disease severity." (PMID 35806986, 2022). "Additionally, alterations in humoral immunity are reported six months following COVID-19 vaccination among patients with inflammatory bowel disease who receive anti-TNF (infliximab, adalimumab) therapy." (PMID 35743695, 2022). "Additionally, CCL3 and TNF were found to increase in critically ill patients with COVID-19 and related to increased morbidity and mortality." (PMID 36531995, 2022). "Assessment of cytokine levels among patients with acute COVID-19 and individuals in the post-COVID-19 period showed significantly higher levels of IL-17 (p=0.0002), TNF-α (p<0.0001) and IL-2 (p<0.0001) in the post-COVID-19 group and higher levels of IL-6 (p<0.0001) in the acute COVID-19 group." (PMID 35846757, 2022).